DISC1 (DISC1 scaffold protein)
Diseases named in the same sentence as DISC1 in open-access papers (continued):
Sharing a sentence is not in itself a finding about the gene and the disease.
schizophrenia (continued). "The DISC1 KO mice might be considered a proxy of prodromal schizophrenia pathophysiology relevant for studying psychotic conversion from the prodromal to the full-blown psychosis phase, suitable for early intervention." (PMID 36831241, 2023). "DISC1 mutant mice have been used to analyze the mechanism of schizophrenia." (PMID 35563598, 2022). "In order to further confirm that aberrant OPCs but not mature OLs contribute to the neuronal defects during the onset of schizophrenia, we cross-bred the DISC1exon3 flox mice with the OL-specific PLPCreERT mice to obtain PLPCreERT:DISC1exon3 fl/+ mice (OL DISC1-Δ3)." (PMID 36131044, 2022). "To understand the G × E effect on polysialylated NCAM expression, in this study, we performed precise measurements of polySia and NCAM using a disrupted-in-schizophrenia 1 (DISC1)-mutant mouse (G), a mouse model of schizophrenia, under acute stress conditions (E)." (PMID 35563598, 2022). "Analysis of mRNA expression of DISC1 splicing variants revealed that Δ3 and Δ7/8 (DISC1 alleles lacking exon 3, or exons 7 and 8) were downregulated during early brain development, but upregulated in schizophrenia brains." (PMID 36131044, 2022). "DISC1 and 22q11.2 microdeletion are established genetic factors of schizophrenia." (PMID 36460658, 2022). "The lncRNA GOMAFU can change the AS events of schizophrenia-related genes DISC1 and ERBB4, and GOMAFU can interact with splicing factors QKI and SRSF1, which may be the mechanism of GOMAFU participating in the AS process." (PMID 34750493, 2022). "Although none of the genes was previously implicated in ASD, one, TRAK1 [chr3:42,244,127 (hg19), A > G], interacts with the known schizophrenia gene DISC1, and one other gene, CLSTN3 [chr12:7310,284 (hg19), G > A], was deemed likely to be pathogenic according to the ACMG guidelines." (PMID 35205252, 2022). "An increasing body of evidence suggests that variation in genes that control the development and maturation of PV interneurons such as NRG1-ErbB4 signaling, DISC1, GRIN1 and DTNBP1, might confer susceptibility to schizophrenia." (PMID 36460658, 2022). "By analyzing both direct and indirect regulation, we provided new insights into how DISC1-Δ3 stabilizes β-catenin and promotes Wnt/β-catenin signaling in the OPCs, which may act as a starting point of schizophrenia pathogenesis." (PMID 36131044, 2022). "This is a similar profile to other “schizophrenia-like” DISC1 and BRINP1 mouse models." (PMID 36407114, 2022). "Furthermore, a specific point mutation of the DISC1 gene (L100P) interacts with MIA during gestation, resulting in an exacerbated phenotype of schizophrenia probably mediated by IL-6." (PMID 35963926, 2022). "Tamoxifen administration removed a single copy of the DISC1 exon 3 from one allele on the double helix, which replicates enhanced expression of DISC1 exon 3 splicing in schizophrenia patients without affecting the expression of full-length DISC1 gene." (PMID 36131044, 2022). "In addition, rare and de novo intragenic variants have been identified in a low proportion of schizophrenia cases, examples including SETD1A and Disrupted-In-Schizophrenia 1 (DISC1)." (PMID 33670154, 2021). "Though Dlx5 and Dlx6 have not been linked to specific disorders, Disc1 (disrupted-in schizophrenia-1) and Cntnap2 have similar functions in cortical interneurons." (PMID 33949949, 2021). "Moreover, OLFM1 is part of the disrupted in schizophrenia 1 (DISC1) protein interactome, variations of which were shown to increase the risk of poorer childhood cognitive performance in people who later developed SCZ." (PMID 34518517, 2021). "Although the mechanism by which NDE1-DISC1 interactions could contribute to schizophrenia remains unclear, it is conceivable that NDE1 contributes to the morphological differentiation of oligodendrocytes by sequestering DISC1." (PMID 33390896, 2020).
schizophrenia (continued). "Moreover, postmortem studies have revealed an increased expression of DISC1 protein in OLs in frontal-parietal white matter region in paranoid schizophrenia." (PMID 32425837, 2020). "Our mechanistic findings of abnormal PV IN function in a Disc1 LI model provide insight into biology that may be relevant to neuropsychiatric disorders including schizophrenia." (PMID 32029441, 2020). "This could be result of an impaired exploratory motor behavior and habituation of exploration in a novel environment, also reported for the DISC1 animal model of schizophrenia." (PMID 32514634, 2020). "Changes in PFC excitation/inhibition balance are associated with behavioral deficits, and DISC1, although no longer considered a valid common risk gene for schizophrenia, has been raised as a tool for the study of endophenotypes of mental disorders." (PMID 32029441, 2020). "We also proposed that disrupting the DISC1-D2R complex with a therapeutic peptide or small molecule drugs could be a novel treatment strategy for schizophrenia." (PMID 32493513, 2020). "Analogously, DISC1 (Disrupted in Schizophrenia 1) is a known gene that codes for a structural protein that is important in the developing cortex and that is involved in mental illness pathologies such as schizophrenia." (PMID 32150898, 2020). "They acknowledge that DISC1 is no longer considered a major risk factor for schizophrenia, yet frame their MD-dACC experiments as pertinent to schizophrenia." (PMID 32029441, 2020). "Although there is still disagreement in the field whether mutated DISC1 is a genetic cause of CMI, there is considerable evidence that DISC1 protein pathology may play a role in schizophrenia and other CMI." (PMID 30723982, 2019). "Despite its name, which reflects a unique finding of a familial aggregation of major mental illness, according to recent investigations, DISC1 is unlikely to be a “genetic” factor causing schizophrenia." (PMID 30617212, 2019). "DISC1 has not shown promise as a common risk gene for schizophrenia; however, research exploring the function of DISC1 in early brain development still represents an avenue to understand a key molecular driver in the neuropathogenesis of mental illness." (PMID 30745562, 2019). "Therefore, reduced prefrontal dopaminergic neurotransmission, which is repeatedly reported in various DISC1 models as well as in DISC1 G × E interaction models, could underlie the emotional and cognitive disruptions in schizophrenia, fitting well to the dopamine hypothesis of schizophrenia." (PMID 31057438, 2019). "Furthermore, a subgroup of postmortem brains of patients diagnosed with affective disorders or schizophrenia expressed significant fractions of DISC1 protein aggregates." (PMID 30723982, 2019). "Moreover, it has been demonstrated that NRG1 also regulates DISC1 expression, thus further worsening the aberrancy of the Akt–mTOR pathway and the pathogenesis of schizophrenia and related behaviors." (PMID 30061532, 2018). "As we advance in our understanding of the genetics of dyslexia, it may be that they become only marginal, historical candidates in the long run, much in the same way that has happened with other disorders, such as DISC1 in schizophrenia." (PMID 30218584, 2018). "Therefore, the involvement of D2R can connect DISC1 and GluN2B and provide a potential target for schizophrenia therapy." (PMID 30233316, 2018). "These expression patterns of the DISC1 and ERRB4 splice variants are comparable to the increased DISC1 and ERRB4 splice variant levels reported in the post-mortem hippocampus from subjects with schizophrenia." (PMID 29657307, 2018). "Our data suggest that an increased polygenic burden for schizophrenia may impact upon regulatory variation of the DISC1 locus in the brain." (PMID 28011714, 2017). "DISC1 gene alterations have previously been linked to psychiatric anomalies, although the gene has not been formally recognized as a schizophrenia risk factor." (PMID 29079805, 2017).
schizophrenia (continued). "We found that DISC1 interacts with Neurexin (NRXN1), which encodes a family of synaptic adhesion molecules implicated as a risk factor of various psychiatric disorders including schizophrenia and autism spectrum disorders." (PMID 29079805, 2017). "Disrupted in schizophrenia 1 (Disc1), pericentriolar material 1 (PCM-1), and human jouberin (Abelson helper integration site 1 (AHI1)) are linked with schizophrenia, hamartin (Tuberous sclerosis 1 (TSC1)) is linked with autism, and pericentrin (PCNT), DCDC2, and Dyx1c1 are linked with dyslexia." (PMID 28125008, 2017). "While 14-3-3 proteins and Disc-1 are known to be associated with schizophrenia, no such evidence exists for TSC1." (PMID 28125008, 2017). "DISC1 is known to interact via its N-terminal globular domain with PDE4B, mutation of which has previously been implicated in neurodevelopmental disorders such as schizophrenia." (PMID 28334933, 2017). "Understanding how relatively subtle changes in the composition of the DISC1 protein may confer behavioral abnormalities is thus important in further elucidating the role of DISC1 in schizophrenia and related mental disorders." (PMID 26728762, 2016). "In support of this statement, one study found that MIA induced a phenotype characterized by strong social impairment specifically in mice overexpressing a double negative form of DISC1, a gene strongly associated to Schizophrenia and ASD." (PMID 27462204, 2016). "The disrupted in schizophrenia 1 (DISC1) gene locus is a particular case." (PMID 26301809, 2015). "This could constitute the mechanism for the polymorphisms in the SLC12A2-associated genes DISC1 and CTNX3 to influence the developmental process and contribute to the aetiology of schizophrenia." (PMID 25889058, 2015). "In addition to their link through DISC1, many of these molecules have their own links to schizophrenia and depression." (PMID 25762938, 2015). "The result that soluble dysbindin-1B interacts with DISC1 suggests that dysbindin-1B and DISC1 may co-exist in aggregates in schizophrenia patients." (PMID 27462430, 2015). "Nonetheless, a direct deficit in neurostructural dynamics caused by either Gomafu, DISC-1 or ErbB4 in patients with schizophrenia has not been established." (PMID 26483630, 2015). "It is important to note, however, that the disorders in which DISC1 is most strongly implicated, namely schizophrenia, bipolar disorder and recurrent major depression, are not characterized by extensive neurodegeneration." (PMID 24092329, 2014). "Common variations in DISC1 may also play a role in schizophrenia and affective disorders in karyotypically normal patient populations." (PMID 25126062, 2014). "Together with thorough further investigations, the findings presented here could provide some insight into how truncation of DISC1 may affect CNS function in humans, for example features such as working memory in schizophrenia." (PMID 24712988, 2014). "DISC1 was discovered in a Scottish pedigree in which a chromosomal translocation that breaks this gene segregates with psychiatric disorders, mainly depression and schizophrenia." (PMID 24027503, 2013). "Interestingly, reducing GSK3β activity was able to correct behavioral deficits in DISC1 mutant mice, strongly implicating DISC1 affects GSK3β in schizophrenia pathogenesis." (PMID 23543703, 2013). "Furthermore, abnormal proteins encoded by schizophrenia susceptibility genes (PRODH, DISC1, DAOA, NRG1, G72) cause oxidative stress and/or hypersensitivity to oxidative stress or mitochondrial dysfunction." (PMID 24027504, 2013). "Further behavioral studies under various experimental conditions are necessary to determine whether these Disc1 mutant mouse lines are suitable animal models of schizophrenia and major depression." (PMID 22348257, 2012). "Furthermore, ITSN1 was identified as a binding partner for DISC1 (disrupted in schizophrenia 1) suggesting a potential role in psychiatric disease as well." (PMID 22558309, 2012).
schizophrenia (continued). "Whether the identification of DISC1 as a FOXP2 target places FOXP2 in schizophrenia-related pathways remains unclear." (PMID 22736078, 2012). "The profile of each individual pathogen is again specific for different types of gene product, but all target key members of the schizophrenia network including dopamine, serotonin and glutamate receptors as well as neuregulin and growth-related or DISC1 related pathways." (PMID 22567321, 2011). "Interestingly, the major diagnosis in the original t(1∶11) DISC1 translocation family was that of recurrent major depression (10 individuals), as well as schizophrenia (7 individuals)." (PMID 21298101, 2011). "Indeed DISC1, neuregulin, ERBB4, FEZ1 or COMT knockout mice display many of the pathological and behavioural symptoms associated with schizophrenia." (PMID 22567321, 2011). "We believe that the results described here, establishing a previously unrecognized role of DISC1 in regulating primary cilia, and revealing ciliary localization of particular schizophrenia-relevant dopaminergic receptors, represent early progress toward this challenging and important goal." (PMID 20531939, 2010). "Although DISC1 mutations are rare and not commonly detected in genome-wide association studies for specifically categorized diagnostic criteria such as schizophrenia, this model has been invaluable for uncovering the mechanisms behind cytoskeletal dysfunction in NDDs in a cross-disease manner." (PMID 40880479, 2025). "To identify risk factor genes that interact with DISC1 in synaptogenesis, we set up a genetic crossing between the DISC1OE flies (hereafter DISC1OE represents the overexpression of DISC1 under tubP-GAL4 driver) and the fly mutants of diverse schizophrenia risk genes." (PMID 39604386, 2024). "Besides, PDE4A was related to heat shock protein B6 (HSPB6), aldehyde dehydrogenase 7A1 (ALDH7A1), A-kinase anchoring protein 1 (AKAP1), adrenoceptor beta 2 (ADRB2), SAG (an arrestin family member which desensitizes GPCR) and DISC1 (disrupted in Schizophrenia 1)." (PMID 38514754, 2024). "Disrupted in Schizophrenia 1 (DISC1) is posited to be involved in synaptic pruning, and an over-pruning of cortical synapses during critical neurodevelopmental periods is hypothesized to contribute to the development of schizophrenia." (PMID 36980961, 2023). "Since others have reported that genetic mouse models of schizophrenia (e.g., Disc1) exhibit alterations in anxiety-like behaviors and locomotor activity compared to their wild-type counterparts, we also assessed whether these behaviors were present in Q22 mice." (PMID 37630824, 2023). "Mutations in DISC1 have been well documented in association with schizophrenia but not ASD." (PMID 35205252, 2022). "However, the complex genetic landscape of this locus, which includes protective and risk variants in interaction, may have hindered consistent conclusions on how DISC1 contributes to schizophrenia (SZ) liability." (PMID 35513527, 2022). "Thus, CRMP1 could be a novel candidate protein for the investigation of schizophrenia mechanisms, which functionally interact with DISC-1 and intersect with the reelin and DISC-1 pathways." (PMID 36430976, 2022). "Notably, reduced expression of T-type channels has been reported in mice upon PVI-specific deletion of the schizophrenia-associated gene FXR1 (FMR1 autosome homolog 1), although potential defects in T-type channel expression specifically in Disc1-mutant mice are unclear." (PMID 36239988, 2022). "Though DISC1 is not considered a common risk gene for schizophrenia by GWAS, DISC1 may play critical roles as a pathological mediator in a wide range of psychiatric disorders." (PMID 33315097, 2021). "Despite the lack of hits for DISC1 in genome-wide association study (GWAS) screens, there is evidence of the role of DISC1 mutations that have been shown to be heritable in the pathology of schizophrenia and related CMIs." (PMID 34921141, 2021).
schizophrenia (continued). "DISC1 dysregulation is not the sole contributing factor to Schizophrenia susceptibility." (PMID 32438615, 2020). "In addition, several ciliary proteins interact with proteins that are known to play a role in neuropsychiatric disorders: PCM1, BBS4 with DISC1 in schizophrenia, bipolar disorder and depression, KIF3A, PCNT with DCDC2 in dyslexia, and PCM, AHI1 with HTT in Huntington disease." (PMID 32973177, 2020). "In addition, the 129S6/SvEvTac strain used in Grid1tm1Jnz lacked the DISC1 gene (disrupted in schizophrenia 1), which is a strong candidate gene that contributes to cause schizophrenia and autism spectrum disorder." (PMID 32078638, 2020). "Besides specific phenotypes such as DISC1 protein pathology, abnormal dopamine homeostasis, and changes in neuroanatomy and behavior, this animal model also shows subtle disturbances in overarching signaling pathways relevant for schizophrenia." (PMID 31150013, 2019). "The identification of this biologically definable schizophrenia subset was achieved by reverse translating PBMC transcripts identified as differentially expressed in tgDISC1 versus littermate control rats as an animal model for an aberrant signaling pathway with DISC1 protein involvement." (PMID 31150013, 2019). "Our findings indicate that overexpressed human DISC1 with schizophrenia-related polymorphisms × JIA by the LPS model is a useful tool that can be used in future studies to investigate the two-hit, synaptic pruning hypothesis of schizophrenia." (PMID 31057438, 2019). "Indeed, when we selected only CSZ patients and HCs, excluding FEP patients, we observed an indirect mediating effect for each SNP on schizophrenia diagnosis via DISC1 expression (rs3738398: effect = 0.135, 95% bootstrap CI = 0.009–0.346; rs10864693: effect = 0.120, 95% bootstrap CI = 0.004–0.313)." (PMID 30923314, 2019). "Interestingly, these SNPs were not directly associated with schizophrenia; however, via a mediation model, they were indirectly associated with the disorder through DISC1 expression." (PMID 30923314, 2019). "Notably, previous investigations in human post-mortem brain and a transgenic rat suggest that protein misassembly of DISC1 could play a role in defining a subset of patients with schizophrenia or other CMI, termed DISC1opathies." (PMID 28275106, 2017). "Considering the clinical relevance of deficits in NRG1 and DISC1 gene function in neurodegenerative and neuropsychiatric disorders (such as schizophrenia, Parkinson’s disease, and Alzheimer’s disease), our findings could be considered proof-of-concept for a new treatment strategy of these diseases." (PMID 28198409, 2017). "Our data suggest that an increased PRS for schizophrenia may impact upon regulatory variation of the DISC1 locus in the brain, implicating a potentially common pathway between polygenic and highly penetrant single locus aetiologies that warrants further investigation." (PMID 28011714, 2017). "Although DISC1 appears to be important for mitochondrial trafficking in neuronal axons, whether DISC1 also impacts mitochondrial trafficking in dendrites, a key locus for altered neuronal function in schizophrenia and other major mental illness, is unknown." (PMID 26553875, 2016). "However, there is an apparent disconnect with genome-wide association studies, which have not linked common variation at the DISC1 locus with schizophrenia or affective disorders in the wider population." (PMID 26405049, 2015). "While the evidence for it being central to disease pathogenesis in the original Scottish family is compelling, recent genome-wide association studies have not found evidence for common variants at the DISC1 locus being associated with schizophrenia in the wider population." (PMID 26405049, 2015). "Furthermore, the gene disrupted in schizophrenia 1 (Disc1) is homozygously inactivated in all 129 mouse substrains, and this genetic mutation may be causally linked to hypo-genesis of CC in these animals." (PMID 25895500, 2015).